ACTB (actin beta)
Diseases named in the same sentence as ACTB in open-access papers (continued):
Sharing a sentence is not in itself a finding about the gene and the disease.
cancer (continued). "However, experiments are needed to show this causative effect and to rule out the possibility that the observed enrichment of ACTB or ACTG1 mutations in these two cancer types reflect a higher tolerance for such mutations compared to other cancer types in which they are therefore less detected." (PMID 32349449, 2020). "The cross-tissue analysis of 12 cancer types revealed that the most stably expressed genes were: PUM1 (SExp = 70), IPO8 (SExp = 61), UBC (SExp = 60), ACTB (SExp = 55), and RPN1 (SExp = 54)." (PMID 30881377, 2019). "We examined, in addition to ACTB and GAPDH, four other reference genes, HPRT1, RPL29, 18S rRNA, and B2M that have been evaluated as reference genes in recent studies for other human cancers." (PMID 20507635, 2010). "A review on the selection of normalizers for RT-qPCR cancer studies recommended that a combination of PPIA and ACTB, HPRT1 (hypoxanthine phosphoribosyltransferase 1), TBP (TATA-binding protein), or GAPDH, or an appropriate combination of three of these genes, should be employed." (PMID 40943534, 2025). "Moreover, the expression of ACTB in stage III and IV of various cancers is higher than that in stage I and II51." (PMID 38649690, 2024). "ACTB and RPS18 displayed a high abundance in cancer and normal tissues." (PMID 36467891, 2022). "However, we did not observe any significant changes in the amplification of nuclear genes, GAPDH (p = 0.1543) and ACTB (0.5629), in the serum EVs DNA from PDAC and non-cancer subjects." (PMID 36323735, 2022). "ASA-A, ASA-B and POPA brought about a considerably higher increase of the PARP2/ACTB mRNA ratio in the BRCA1-null UWB1.289 than in the BRCA1 wild-type UWB1.289 + BRCA1 cancer cells, with the ASA-B begetting a 140- to150-fold increase of the PARP2/ACTB mRNA ratio in UWB1.289 cells." (PMID 34440232, 2021). "We also found that ACTB expression was higher in stage III and IV compared with stage I and II in several cancers including KICH, KIRC, STAD, TGCT, THCA, ACC and BLCA, indicating ACTB might promote tumor development." (PMID 34486492, 2021). "Secondly, a cancer-associated D1425N mutation of CSB, which sensitizes cells to cisplatin, does not affect RNAPII occupancy at PPP sites of ACTB, GAPDH and RPL13A genes." (PMID 33806087, 2021). "ACTB might regulate tumor metastasis and invasion by NF-κB and Wnt/β-catenin pathways in HNSC and other cancers, while further validation in different cancers is needed." (PMID 34486492, 2021). "Based on GEO datasets using prognoscan, we found high ACTB expression was correlated with poor OS, RFS, disease-specific survival (DSS), distant metastasis free survival (DMFS), distant recurrence free survival (DRFS) and DFS in various cancers (All P < 0.05)." (PMID 34486492, 2021). "The treatment of the tested cancer cell lines with the 3-AB agent alone generated non-significant alterations in the PARP1/ACTB mRNA cellular content (data not shown)." (PMID 34440232, 2021). "Consequently, as was revealed, the more sensitive a cancer cell line to the cytostatic and cytotoxic effects of a tested compound, the higher the increase of the relative PARP1/ACTB and PARP2/ACTB mRNA ratios observed." (PMID 34440232, 2021). "The low frequency of ACTB and ACTG1 mutations across all cancers is in part explained because they are not found in many cancer types (ACTB: in 46 out of 75, ACTG1: in 29 out of 75)." (PMID 32349449, 2020). "However, multiple published studies have used different genes (e.g., KRAS, BRAF, APP, ACTB, GAPDH, 16s rRNA, ALU, LINE 1) as biomarkers to determine cfDI in various cancers." (PMID 31620364, 2019). "In Proteoglycans in cancer pathway, FZD9, GPC1, PAK1, FZD1, and ACTB were extracted." (PMID 30733969, 2019). "GAPDH and ACTB were identified as cancer essential genes more often by CES than by other methods at the given ranking thresholds, resulting in the largest AUC for both genes (96.5% and 97.9% for GAPDH and ACTB, respectively)." (PMID 31732481, 2019).
cancer (continued). "Another 6 genes, SUB1, SLC2A1, CTNNB1, ACTB, HSP90B1, and CLTC were selected from the remaining unknown migration-related genes in order to confirm their relationship with cancer cell migration." (PMID 28640862, 2017). "By contrast, GAPDH or ACTB, which are widely used as RGs are not suitable in this type of cancer as their expression is significantly different in non-photodamaged skin and the different type of NMSC." (PMID 28852586, 2017). "Furthermore, the expression of SLC2A1, CTNNB1, ACTB, and CLTC were significantly changed in only one type of cancer during migration." (PMID 28640862, 2017). "While three of the chimeras (ACTB->POTEM, ACTB->POTEE and SP100->HMGB1) have been found in normal population, three of the chimeras (C2orf27A->NBEA, HILPDA->EFCAB3, FARSB->TRIM61) were previously identified only in cancer samples." (PMID 25133550, 2014). "For the Test Cancer BioChip, the negative controls employed included non-targeting, ACTB, GUSB, GAPDH, RPLP0, TFRC and cyclophilin siRNA as well as no siRNA." (PMID 23049944, 2012). "It was preliminarily predicted that NR could regulate the targets of CASP3, AKT1,ESR1,ACTB,MAPK3 and may modulate various pathways like estrogen signaling, thyroid hormone signaling pathway, prolactin signaling pathway, proteoglycan in cancer pathway, endocrine resistance pathway." (PMID 36401485, 2022). "Oncomine and TCGA results demonstrated increased expression of ACTB in multiple cancers like head and neck cancer, leukemia, pancreatic cancer, LIHC, KIRC compared with normal tissues, and ACTB expression was lower in several cancers like lung and prostate cancers." (PMID 34486492, 2021). "In order to preserve the heterogeneities among tumors to the most extent, ACTB and GAPDH were avoided using as reference genes due to the fact that cytoskeleton and energy metabolism might be greatly deregulated among cancer individuals (Xiang, Chen & Fu, 2017; Stine & Dang, 2013)." (PMID 29915691, 2018). "They concluded that ACTB might be involved in the pathogenesis of certain cancers; that ACTB might not be a valid reference protein for quantifying expression levels; and that ACTB might be a potential biomarker of cancer." (PMID 29439554, 2018). "Taken together, cancer-associated up-regulation of the reference genes used in the present study was (i) definitely present (PGK1), (ii) vaguely present (GAPDH) or (ii) absent (ACTB)." (PMID 26468005, 2015). "ACTB was not included in the extended list of candidate genes only because it had high intergroup variation between normal epithelium samples from cancer and cancer-free patients." (PMID 23876162, 2013). "Interestingly, another well-known housekeeping gene ACTB was ranked 14 out of 20,501 genes, suggesting that both GAPDH and ACTB genes might be unsuitable housekeeping genes for gene expression experiments, particularly in cancer studies." (PMID 31324856, 2019). "One interesting suggestion put forth by a 2002 cancer study was that the nonmetabolic (such as UBC or B2M) and structural (such as β-tubulin or ACTB) HKGs demonstrated lesser level of variation than the metabolic HKGs." (PMID 40943534, 2025). "Interestingly, we observed that GAPDH, GUSB, IPO8, RPL13, RPL32, and UBC genes, as well as RPLP0 + TBP, RPL13 + RPL32, RPL13 + RPLP0, and ACTB + TBP RG pairs, were the only assays whose expression did not depend (P > 0.05) on cancer progression." (PMID 25225161, 2014). "However, GAPDH, ACTB, and PPIA have not been included in the census of human cancer genes." (PMID 40943534, 2025).
tumor (106 papers, 2005 to 2025). "While our study utilized total cfDNA quantification via ddPCR targeting ACTB, an alternative approach is mutation-specific circulating tumor DNA (ctDNA) tracking, which detects tumor-derived mutations for enhanced specificity." (PMID 41256319, 2025). "In our study, Treg subtype C2 (ACTB+ Treg) had high expression of proliferation metabolism and invasion metastasis-related signature genes, which are closely associated with tumor-promoting effects." (PMID 37519793, 2023). "Furthermore, the presence of mutations in ACTB in both tumor and metastatic samples suggested an association with the impaired ability of tumor cells to repair DNA damage." (PMID 37744240, 2023). "Survival analysis of these genes in tumour samples identified seven genes that were associated with prognosis, including ACSL5, HSD17B11, CCL5, NCF2, PSME1, ACTB, and CYBB." (PMID 40299520, 2025). "The MCS exhibited improved viability and a gene expression profile associated with aggressive tumor characteristics, including increased expression of genes linked to cell survival and motility, such as COL1A1, MSN, HIF1A, TUBB, and ACTB." (PMID 41516217, 2025). "Of note, LEADR was localised within nuclei of tumour cells as assessed by fluorescence in situ hybridization (FISH) using MIR205HG or control ACTB (β-actin) probes, whereas the nuclei of T24 and TCCSUP cells were negative for MIR205HG." (PMID 40461454, 2025). "ACTB was positively correlated with tumor purity, B cells, CD4+ T cells, CD8+ T cells, neutrophils, macrophages and dendritic cells." (PMID 39896807, 2024). "Previous studies have shown that ACTB deregulation was usually detected in tumors and affected the polymerization of ACTB at the leading edge in tumor cells, resulting in tumor progression and metastasis." (PMID 36674696, 2023). "The mRNA markers were tested in parallel to cfDNA using the reference gene ACTB and tumor-specific RASSF1A-M." (PMID 37046768, 2023). "The down-regulation of ARID1A, which is a tumor suppressor gene, induces expression of angiogenesis-related genes (particularly VEGF and FGF2) and stimulates angiogenesis independently of ACTB encoding β-actin." (PMID 38017409, 2023). "To apply the prescreening process as a single-tube reaction, we performed multiplex RT-PCR analyses using CEACAM5, HMGB3, and ACTB probes with different fluorescence dye formats, which resulted in consistent tumor-specific detection." (PMID 36397035, 2022). "We investigated SOX9 protein levels in the same 33 pairs of human CRC tumors and matched mucosa, 2 tumor samples were omitted due to protein degradation observed in ACTB NI‐WB." (PMID 34919787, 2022). "This corresponds to an 18.4-fold increase in ACTB expression between weeks 1 and 2 of tumor development." (PMID 34868914, 2021). "ACTB expression is high in tumor tissues and cell lines; its deregulation in tumors is associated to loss of polarization and major invasiveness and metastatic potential, also described in metastatic breast cancer." (PMID 34320944, 2021). "∆Ct, which was defined as the difference between the Ct values of the targets (MSPR1 and MSPR2) and the reference gene ACTB also varied significantly among normal tissues and tumor samples." (PMID 33955718, 2021). "ACTB expression significantly increased after the first week of tumor progression and remained elevated until the end of the experiment (p = 0.0007, One-way ANOVA; Tukey’s post-test: Week 1 vs Week 2: p = 0.0014, Week 1 vs Week 3: p = 0.0009)." (PMID 34868914, 2021). "Expression study of LGR5, HES1 and ATOH1 were performed by quantitative PCR (QPCR) based on comparative Cq method after normalization to adjacent non tumor tissues and ACTB as a reference gene." (PMID 34582650, 2021). "ACTB has been reported to form fusion genes in some human neoplasms, and fusion genes involving GAPDH have also been reported in evolutionarily low organisms." (PMID 34966852, 2021).
tumor (continued). "Their Ct values ranging from 28.71 to 37.19 indicate comparatively lower MET transcript levels than that of ACTB in tumor samples." (PMID 31369639, 2019). "In the quantitative RT-PCR (qPCR) analysis, CFC1 expression normalized by ACTB was also strongly up-regulated in the tumor spheres of all three cell lines." (PMID 28620148, 2017). "A similar pattern of reduction in MMR transcript levels was observed in tumor samples using ACTB as endogenous control." (PMID 25938433, 2015). "Among malignant samples, the expression of reference genes was substantially equivalent among tumor grade groups for ACTB, PPIA and TBP." (PMID 25473950, 2014). "We divided 35 subjects by HOTAIR expression into two groups: high expression (n = 12) and low expression (n = 23), according to a HOTAIR/ACTB ratio of 1.368 in tumor tissues, obtained by the ROC method." (PMID 24591352, 2014). "Expression of IPO8, RPL4, TBP, RPLPO, and ACTB had the least variation in expression across the tumour samples according to GeNorm, NormFinder, and BestKeeper." (PMID 24001041, 2013). "Nude athymic mice xenografted with HT29 cells were sacrificed at different time points, tumours were weighted and ctDNA concentration in plasma samples determined using the HuACTB 133 primer pair that targets a 133 bp sequence in the human ACTB gene." (PMID 21909401, 2011). "Tumor tissue derived from patient #1 showed a very high methylation rate of 291% (referred to ACTB) and 46% (referred to total SHOX2 copies), respectively, as well as a strong copy number amplification of the SHOX2 gene (4.9 fold)." (PMID 21426551, 2011). "THBS4 expression normalised to ACTB was generally quite low in both peritumoural normal mucosa and in tumours." (PMID 20846368, 2010). "Additionally, proteins associated with neoplasm invasiveness and metastasis (SRC, ALDOA, ACTB, MAPK1, and RAC1) and those mediating epithelial to mesenchymal transition (annexin A1, Hsp27) were upregulated in the LNM group." (PMID 41193833, 2025). "Four weeks post-intracardiac inoculation, qPCR was performed on homogenized femora for human CDKN1B (gene name for p27), and normalized to ACTB (human tumor housekeeping gene) and Hmbs (mouse housekeeping gene) to quantify p27 specifically in bone-disseminated human tumor cells." (PMID 38409028, 2024). "ACTB might also regulate tumor metastasis and invasion through the NF-κB and Wnt/β-catenin pathways." (PMID 37124724, 2023). "However, increasing evidence has recently shown that cytoskeletal actin can regulate the adhesion and movement of tumour cells, and ACTB can influence the invasion and metastasis of tumour cells via polymerisation and localization." (PMID 37691922, 2023). "In the TCGA-HNSC cohort, we found that ACTB, MAP2K1, PARVB, and PDGFA were upregulated in tumour tissues, suggesting that gene expression may be associated with tumourigenesis." (PMID 37691922, 2023). "F. nucleatum burden was determined using probe-based quantitative PCR (qPCR) on DNA from colonic normal and tumor tissue of Fn7-1 neonatally exposed ApcMin/+ mice, using previously characterized primers that target F. nucleatum nusG17,18 and mouse ActB, to normalize to tissue DNA copies." (PMID 34781821, 2021). "When signatures from plasma- and ascites-derived sEVs were compared we found significant differences in expression of COL5A1, AEBP1, TIMP3, and ACTB at week 3 of tumor progression, suggesting that ascites-derived sEVs are likely a stronger indicator of tumor presence compared to plasma-derived sEVs." (PMID 34868914, 2021). "For instance, ACTB is a highly conserved protein well-known for its regulation of the actin cytoskeleton and adherens junctions, which are necessary for both normal and tumor cell migration." (PMID 28640862, 2017). "While many chemotherapeutic agents currently act by disrupting the cytoskeleton, directly targeting ACTB with siRNA may have similar cytotoxic effects on the tumor cells." (PMID 23049944, 2012).
tumor (continued). "Two different endogenous controls (GAPDH and ACTB) were employed to reduce variability that might exist between normal, hyperplastic and tumor-containing mammary tissues." (PMID 17626637, 2007). "Identified as most frequently mutated housekeeping gene in HCC tissue, mutant ACTB 3′UTR acted to inhibit miR-29a by direct interaction, whereby miR-29a target gene MCL1 apoptosis regulator, BCL2 family member (MCL1) was up-regulated to bolster tumor progression." (PMID 33803804, 2021). "The levels of PEX ACTB mRNA are expected to reflect the total amounts of PEX being related to proliferative activity and rapid tumor growth." (PMID 39867897, 2024). "In our study, the expression stability of five reference genes ACTB, ALAS1, GUSB, HMBS, and RPL29 were investigated to determine the CRM1 gene expression profile in tumor tissues and normal tissues by NormFinder analysis." (PMID 38031942, 2023). "Results showed that ACTB, DSTN, FLNA, IQGAP1, MYL6, and TLN1 were overexpressed in normal tissues, while CD2AP and INF2 were overexpressed in tumor tissues." (PMID 37325625, 2023). "Lymphocyte genes in MM samples which were very downregulated compared to those in HC samples included MYH9, RN7SL2, ACTB, AHNAK and FLNA, which play important roles in cell motility, cell structure, cell migration and tumour metastasis." (PMID 37914759, 2023). "Sequencing the Actin genes (ACTB and ACTG1) from the tumor organoid derived from patient 8, the source of the PCs encoding antibody 8-3, showed no mutations in the protein-coding regions, verifying the self-antigen nature." (PMID 37751306, 2023). "After using the Livak method and normalizing with the ACTB gene, it was found that DLX1 and DSC1 expression was lower in tumor tissues than in blood tissues." (PMID 37876438, 2023). "Our previous results assessing reference genes in Sq-NSCLC showed that GAPDH gene expression was diverse and unstable in tumor and tumor-adjacent normal tissue samples, whereas POLR2A and ACTB expression levels were the most stable among analyzed samples." (PMID 36142417, 2022). "Our results agree with this study because our analyses significantly improve the variation when we used the combination of ACTB and HPRT1, so this result supports their use in further gene expression studies in MM tumour samples for more reliable results." (PMID 34940125, 2021). "The tumor expresses a fusion gene between FOSB and either SERPINE1, ACTB, or WWTR1, which results in an overexpression of FOSB." (PMID 33194900, 2020). "One such issue is the influence of knockout of ACTB or ACTG1 on the cell proliferation rate, signaling pathways involved in tumor progression, and nuclear processes regulated by actin." (PMID 32326615, 2020). "In particular, we found that TMEM30A regulates several migration-related genes including SUB1, SLC2A1, CTNNB1, ACTB, and CLTC during tumor migration, which further demonstrates the effectiveness of our proposed method." (PMID 28640862, 2017). "In normality test, ACTB, HPRT1, and 18S rRNA in 'normal stomach tissues' group and all genes except for GAPDH in 'tumor stomach tissues' followed normal distribution by KS-test." (PMID 20507635, 2010). "Amongst seven commonly used classical housekeeping genes, we found that expression levels of ACTB, GAPDH, GUSB and 18S rRNA, significantly differed between tumor and normal tissues on the basis of the examination of raw CT values." (PMID 19257903, 2009). "ACTB, GAPDH and GUSB mRNA levels are significantly increased in tumor samples, with changes of about 3.6, 3.5 and 4.7 fold, respectively; while 18S rRNA was revealed to be slightly diminished in tumor samples, in a proportion of approximately 13%." (PMID 19257903, 2009).